PKD1 (polycystin 1, transient receptor potential channel interacting)
Diseases named in the same sentence as PKD1 in open-access papers (continued):
Sharing a sentence is not in itself a finding about the gene and the disease.
cyst (continued). "At all time‐points, we found a trend consistent with that observed in the cyst‐induced chronic injury, showing that Kim1 expression was less in double KO mice than in Pkd1 KO." (PMID 31038742, 2019). "Pkd1 was inactivated by tamoxifen injection at postnatal day 10 and 11 (P10, P11), within the critical developmental period for cyst formation and kidneys were dissected at P21 and P28." (PMID 31059522, 2019). "Inhibition of glutamine metabolism in both Lkb1/Tsc1 and Pkd1 mutant mice significantly reduces cyst progression." (PMID 29483507, 2018). "PKD1-null renal epithelial cells and ciliated cyst-lining epithelial cells derived from ADPKD patients showed a lack of flow-induced increases in intracellular calcium." (PMID 29463793, 2018). "Excitingly, treatment of mouse models of PKD, including Pkd1 mutants, with drugs that block glutaminolysis mitigates cyst formation in vivo suggesting a potential avenue for PKD therapeutics." (PMID 29483507, 2018). "We found through network studies of gene expression patterns of young mice that metabolic pathways were important factors in the critical switch that defines the kinetics of cyst formation after Pkd1 inactivation." (PMID 29426897, 2018). "We confirmed cyst progression upon reduction of Pkd1 or Pkd2 in adult renal collecting duct epithelia." (PMID 29443690, 2018). "In accordance with this study, we found that metformin inhibited early cystogenesis in zebrafish pkd2 morphant embryos, indicating that metformin can inhibit cyst growth in both PKD1 and PKD2 animal models." (PMID 28769124, 2017). "Knockdown of either Pkd1 or Pkd2 in mIMCD cells resulted in remarkable defects of F-actin structure and accelerated cyst growth in 3D culture." (PMID 29074972, 2017). "The pathological similarities between Pkd1 cKO disease and ADPKD include renal manifestations such as progressive cyst growth accompanied by fibrosis and loss of kidney function, as well as liver cyst formation." (PMID 27356569, 2016). "We have also examined the effect of altering the extent of Pkd1 deletion on cyst growth by manipulating the dose of tamoxifen." (PMID 27356569, 2016). "Knockout of the polycystic kidney disease genes PKD1 or PKD2 induces cyst formation from kidney tubules." (PMID 26493500, 2015). "Among the Pkd1−/− mice, there was some heterogeneity in cyst development between individual animals, in concordance with the basic biology of the disease and previous reports using the model." (PMID 26528438, 2015). "Mutations of PKD1 and PKD2 induce cyst formation in the kidney, and cyst formation in part arises because of derestricted cell proliferation." (PMID 26579493, 2015). "It is caused by mutations in the PKD1 and PKD2 genes, and manifests as progressive cyst growth and renal enlargement, resulting in renal failure." (PMID 25491204, 2014). "Pkd1 mutant cells enter S phase more frequently than wild-type cells, leading to enhanced proliferation and cyst formation." (PMID 23052657, 2013). "First, we targeted a poorly understood postnatal renal maturation stage that we had previously shown plays a critical role in determining the rate of cyst formation in response to acquired Pkd1 inactivation." (PMID 23209428, 2012). "We used this line to determine that Pkd1 inactivation prior to P12 results in cyst formation within 7–21 days, whereas inactivation on or after P14 results in cyst formation only after 4–5 months." (PMID 23209428, 2012). "Rodent model studies with aberrant Prkcsh, Sec63, Pkd1, Pkd2, and Pkhd1 genes indicate that cyst formation can generally be modulated by altering the expression of Pkd1, implying that polycytin-1 plays a central or rate-limiting role in both PLD and PKD." (PMID 22242024, 2011). "Genome wide transcriptome reprogramming and the possible roles of micro-RNAs (miRNAs) that affect the initiation and progression of cyst formation in the Pkd1-/- have yet to be studied." (PMID 21518438, 2011).
cyst (continued). "In human polycystic kidney disease, patients are heterozygous for either PKD1 or PKD2 mutations and suffer from cyst formation and eventual kidney failure." (PMID 18454189, 2008). "To therapeutically recapitulate this effect, we developed a steric-blocking oligonucleotide that occludes the motif, stabilizes PKD1 transcript levels, increases PC1 expression, and mitigates cyst-pathogenic events in both murine and patient-derived ADPKD cells." (PMID 41558825, 2026). "Interestingly, simultaneous knockout of both Pkd1 and Kif3a reduces cyst severity compared to Pkd1 deletion alone." (PMID 40801635, 2025). "We then questioned whether the well-tolerated KCa3.1 inhibitor senicapoc could slow cyst growth in cultured metanephroi, similarly to Pkd1 genetic inactivation." (PMID 41122971, 2025). "Genetic inactivation of Kcnn4 in Pkd1–/– metanephroi markedly delayed cyst initiation and growth." (PMID 41122971, 2025). "The Han:SPRD-Cy rat, although lacking a defined mutation in Pkd1 or Pkd2, exhibits slowly progressive cyst formation and has been used extensively in long-term pharmacological and dietary intervention studies." (PMID 40801635, 2025). "Senicapoc (5–20 μM) dose-dependently reduced cyst area in Pkd1–/– metanephroi." (PMID 41122971, 2025). "It is unclear, however, whether long-term maturation also enables cyst formation in PKD1+/- and patient-derived CD organoids." (PMID 40722835, 2025). "We therefore assessed whether the KCa3.1 agonist SKA-111 modulates cAMP-stimulated cystogenesis or cyst enlargement in Pkd1+/+ or Pkd1–/– metanephroi." (PMID 41122971, 2025). "Pkd1 knockout led to severe kidney failure, massive cyst formation, and death within two months." (PMID 40136708, 2025). "These include transcriptional and translational regulators of PKD1/PKD2, modifier genes (e.g., cyst formation, type IV collagen), and genetic variants linked to chronic kidney disease (CKD) risk factors such as obesity, dyslipidemia, hypertension, and diabetes." (PMID 40051696, 2025). "In PKD, cyst development occurred with reduced expression of Pkd1." (PMID 41300696, 2025). "According to the genetic mechanism proposed in ADPKD of a “two hit” event, by which there is a somatic inactivation of the remaining wildtype allele, cellular PKD1/PKD2 functional activity may fall below a critical threshold, and cyst initiation ensues." (PMID 39940890, 2025). "Additionally, targeting STING with the specific inhibitor C-176 delays cyst growth in both an early-stage, aggressive Pkd1 conditional knockout mouse model and a milder, long-lasting Pkd1 mutant mouse model." (PMID 39456148, 2024). "In conclusion, this study identifies that STING is a key regulator of cyst progression in ADPKD, in that genotoxic stress stemming from Pkd1 gene mutation contributes to dysregulated STING mediated cellular processes, including inflammation, microphage recruitment, apoptosis, and fibrosis." (PMID 39456148, 2024). "Notably, about 10% of patients with atypical or “class 2” cyst distributions, described as unilateral, segmental, asymmetric, lopsided, or with atrophy, were excluded from the Mayo Clinic classification, but have a mild prognosis and are less likely to have a pathogenic PKD1 or PKD2 variant." (PMID 38707833, 2024). "We show that knockout of CD74 delays cyst growth in Pkd1 mutant kidneys." (PMID 38534333, 2024). "Therefore, we compared our data to models differing in Cre expression, target gene (Pkd2 vs. Pkd1), age and method of induction, age at sacrifice, cyst burden at time of collection, and number of mice used for analysis." (PMID 39666736, 2024). "In 2020, Shohei Kuraoka and colleagues demonstrated cyst formation in ureteric bud organoids derived from iPSCs with homozygous deleted PKD1, as well as in ureteric bud organoids generated from heterozygous mutant iPSCs and from a patient with ADPKD, all upon cAMP stimulation." (PMID 39056771, 2024).
cyst (continued). "We explored whether MNPs can target cystic kidney tubules and whether rapamycin-encapsulated-MNPs (RapaMNPs) can slow cyst growth in Pkd1 knockout (KO) mice." (PMID 38956234, 2024). "This suggests that the acute derepression of Pkd1/Pkd2 may prevent disease onset or even halt cyst growth in established PKD." (PMID 39595570, 2024). "Fer-1 inhibited ferroptosis and delayed cyst growth in PKD1-mutant mice." (PMID 37739961, 2023). "Using several models of renal cystic disease, including those associated with loss of folliculin and polycystin-1 (PKD1) activities, it was observed that nuclear TFEB translocation and functional responses associated with TFEB activation characterize cyst-lining epithelia." (PMID 36794754, 2023). "Furthermore, Pkd1−/− mice treated with dopamine receptor antagonists did exhibit cyst reduction and increased body weight and activity." (PMID 37217845, 2023). "Interestingly, a recent report showed that the application of the CFTR-corrector VX-809 (Lumacaftor) in a Pkd1 knockout and the Pkd1RC/RC mouse model reduced cyst growth." (PMID 37686084, 2023). "Intriguingly, loss of PKD1 function in ADPKD enables the epithelial monolayer to increase the transit of fluids into the cyst and to form a non-leaky barrier that can withstand high hydrostatic pressure within the cyst." (PMID 37542051, 2023). "While PC1 has been established as a central player in cyst formation within the genetic interaction network for polycystic kidney and liver diseases, the observed Pkd1 null-like phenotype in the digenic mutants cannot be explained by reduced levels or maturation of PC1V." (PMID 37845212, 2023). "Two Pkd1 mouse models, each with defective GPS cleavage of PC1 due to a different missense mutation, have demonstrated that cleavage is essential for preventing cyst formation." (PMID 36406261, 2022). "Furthermore, acute pharmaceutical blockade of Pkd1/2 cis-inhibition prevents cyst onset and stabilizes established PKD in mice." (PMID 35965273, 2022). "Valproic acid also reduced cyst growth in a Pkd1 mouse model." (PMID 35847973, 2022). "Furthermore, low micromolar concentrations of H2-GMZ were effective in inhibiting cyst formation in a Pkd1 mutant mouse metanephric organ culture model in which a number of processes mediate the growth and enlargement of cysts in response to cAMP." (PMID 35979967, 2022). "We then investigated the effects of suramin on cyst formation in Pkd1-miR Tg mice." (PMID 35955634, 2022). "We found that the expression levels of both markers were gradually increased in cyst-lining epithelial cells in Pkd1 knockout kidneys, especially at postnatal day 21, while they were only localized in the interstitium in Pkd1 heterozygous mouse kidneys and early-stage Pkd1 mutant mouse kidneys." (PMID 36611841, 2022). "However, cyst growth rate over time is the same in Pkd1 and Pkd2 patient populations, suggesting that the difference in disease progression is due to cyst initiation." (PMID 35253003, 2022). "To test whether BA is effective in ADPKD to reduce cyst size in vivo, we used an early Pkd1 conditional KO mouse model of rapidly progressive kidney cystic disease, similar to that described previously." (PMID 36504724, 2022). "Therefore, the aim of the present study was to investigate the pharmacological effects and the detailed mechanisms of GA in slowing MDCK cyst enlargement and Pkd1 mutant cell proliferation." (PMID 35744960, 2022). "Injections of miRNAs precursors decrease the rate of cyst growth in Pkd1 knockout mice." (PMID 35328738, 2022). "Moreover, blockade by RGLS4326 of Pkd1/2 cis-inhibition prevented cyst onset and stabilized existing cysts in mice." (PMID 36203940, 2022). "In contrast, the miR-17 miRNA family becomes activated in PKD models, where it appears to mediate Pkd1 repression well into adulthood, as evidenced by the attenuation of cyst growth by the anti-miR-17 drug RGLS4326, even if the treatment is initiated at later stages of the disease." (PMID 35965273, 2022).
cyst (continued). "The iPSC-derived UB showed PKD1 dose-dependent cyst formation in PKD modeling." (PMID 36551987, 2022). "Moreover, in PN24 (Pkd1−/−) ADPKD cultures there was a substantial decrease in cyst size in the cultures treated with BA (middle) or SB-204990 (right) as compared with vehicle control (left)." (PMID 36504724, 2022). "Postnatal day 14 is a critical time point for cyst progression in Pkd1 conditional knockout mice." (PMID 36611841, 2022). "Thus, whole mouse kidney single-cell transcriptional atlases of Pkd1 homozygous kidneys will represent an important step for detailed investigations of the roles of specific genes and regulatory pathways in cyst initiation and development." (PMID 36611841, 2022). "Knockout of PKD1 or PKD2 induced cyst formation from kidney tubules in this model." (PMID 36551987, 2022). "We performed PKD1 and PKD2 mutation analysis using DNA from cyst cells." (PMID 35965273, 2022). "Indeed, Pkd1-miR Tg mice treated with suramin had significantly reduced cyst indices (21.4 % reduction) compared with vehicle-treated mutant mice (p < 0.001)." (PMID 35955634, 2022). "Moreover, acutely blocking Pkd1/2 cis-inhibition, including after cyst onset, attenuates murine PKD." (PMID 35965273, 2022). "Because the CD-PC-novel cell population was only identified in day 14 kidneys, especially in Pkd1 homozygous kidneys, the upregulation of Cenpf may be one of the critical factors in promoting cyst progression at this time point." (PMID 36611841, 2022). "Conditional double knockout of SIRT1 and Pkd1 delayed cyst growth in Pkd1flox/flox:Ksp-Cre mice." (PMID 36120538, 2022). "In addition, treatment of Pkd1-mutant mice with a glutaminase inhibitor in utero (by administration to the mother) and postnatally (up to P10) slowed cyst progression." (PMID 33758231, 2021). "With virtual screening, Madin-Darby canine kidney (MDCK) cyst model, embryonic kidney cyst model and kidney-specific Pkd1 knockout mouse (PKD) model, we identified obacunone as a candidate compound for ADPKD drug discovery from a natural antioxidant compound library." (PMID 35052542, 2021). "In addition, treatment with Pkd1-null cell EVs/exosomes not only increased cyst lining epithelial cell proliferation but also the surrounding interstitial cell proliferation as in Pkd1RC/RC mice." (PMID 34315885, 2021). "Of note, cyst formation in TSC2−/− AML organoids did not involve loss of polycystin 1 (PKD-1) expression, as indicated by the similar mRNA levels detected in our organoid RNAseq analysis." (PMID 34764250, 2021). "As cyst initiation is assumed to depend on the dosage of functional Polycystin 1, the combination of two hypomorphic variants could additively reduce the PKD1 function below a critical threshold to result in clinically apparent disease." (PMID 34249099, 2021). "The inhibition of mitochondrial function by anti-miR~17-92 attenuates disease progression in ADPKD mouse models irrespective of the mutated gene (Pkd1 or Pkd2), the type of mutation (null or hypomorphic) or the dynamics of cyst growth." (PMID 34901057, 2021). "Mechanisms of cyst expansion in ADPKD and the associated increase in TKV are based on reduced intracellular Ca2+ influx caused by mutations in either PKD1 or PKD2, increased cellular adenosine 3′, 5′-cyclic monophosphate (cAMP) levels, and aberrant Ras/Raf/ERK activation." (PMID 33471240, 2021). "Ginkgolide B was also found to inhibit cyst growth in MDCK cyst model and in Pkd1 knockout mice." (PMID 33986666, 2021). "The increase in cystic index in response to smoking suggests that the tobacco proproliferative effect, although not specific to Pkd1 deficiency, is particularly important at the cyst-lining-cell level, playing an essential role in smoking-induced cyst growth." (PMID 34262092, 2021).
cyst (continued). "Studies of creER-mediated models of conditional inactivation of PKD1 gene will help to further elucidate the cyst formation process during disease and are expected to reveal whether drug targets are cell-source specific." (PMID 34815804, 2021). "A key question is after a second hit if the Pkd1 homozygous mutant renal epithelial cell can affect the cell function of neighboring indirect-contact Pkd1 heterozygous renal epithelial cells and fibroblasts, leading to cyst expansion." (PMID 34315885, 2021). "Interestingly, the mitochondria from PC2 knock-down (KD) cyst-modeling cells exhibit altered metabolic capacity and show a high degree of fragmentation, which they have in common with PKD1; however, an increased level in PCG-1α was shown in PC2 KD cells." (PMID 34901057, 2021). "Interestingly, cyst growth and cystic index (ratio of cyst volume to TKV) varies significantly between the PKD1 and PKD2 genotypes, as patients within the PKD1 population tend to develop cysts earlier." (PMID 32940759, 2021). "The functional relevance of these findings to ADPKD pathogenesis was confirmed using the selective ROCK inhibitor hydroxyfasudil in vitro by 3D cyst assays using human-derived PKD1 cystic cells and in vivo using a previously reported Pkd1-inducible mouse model." (PMID 32663194, 2020). "In addition to regulating the expression of the Pkd1 gene in renal epithelial cells, we found that p68 was upregulated in cystic renal epithelial cells and cyst lining epithelia in Pkd1 mutant mouse kidneys and ADPKD kidneys." (PMID 32724471, 2020). "A subsequent study showed that glutamine-dependence caused by ablation of Lkb1 in combination with ablation of Tsc1 gene resulted in very aggressive cystogenesis in a mouse model and inhibition of glutamine metabolism in both Lkb1/Tsc1 and Pkd1 mutant mice significantly reduced cyst progression." (PMID 32847032, 2020). "These ADPKD iPSCs may provide a powerful model to study PKD1 function and the involvement of the second hit in cyst formation and kidney development in vitro." (PMID 32163234, 2020). "Mouse inner medullary collecting duct Pkd1−/− cells (mIMCD3-Pkd1−/−) were cultured in an extracellular matrix-based hydrogel in 384-well plates, and cyst swelling was induced by addition of forskolin, an inducer of cAMP production mediated via adenylyl cyclase." (PMID 32015419, 2020). "Finally, the ROCK inhibitor hydroxyfasudil reduced cyst expansion in both human PKD1 3D cyst assays and an inducible Pkd1 mouse model." (PMID 32663194, 2020). "Our data confirmed that the dosage/threshold of functional PKD1 protein might be critical for cyst initiation." (PMID 32457805, 2020). "In Pkd1 mutant mice the authors could show aberrant mitochondria in the cyst-lining epithelial cells with a reduced mitochondrial mass and a following reduction in mitochondrial respiratory chain complexes." (PMID 32847032, 2020). "In this work, we first wanted to test whether genetic inhibition of Hdac5 could also reduce cyst formation in Pkd1–/–mice after birth." (PMID 31059522, 2019). "Since renal injury accelerates cyst formation in Pkd1 KO mice 8, 21, 22, 23, 24, we wondered whether prolonged survival observed in the double KO group treated with DCVC could be due to delayed cyst initiation." (PMID 31038742, 2019). "Indeed double KO mice had significantly reduced fibrosis and leukocytes infiltrates compared with Pkd1 KO mice even though cyst formation was comparable." (PMID 31038742, 2019). "We confirmed that nephrotoxic injury can accelerate cyst formation in Pkd1 mutant mice." (PMID 31038742, 2019). "This type of cyst also formed in monkeys with near-complete deletion of PKD1 and in mosaics." (PMID 31822676, 2019). "To investigate whether trehalose treatment prevents cyst growth in Pkd1 miR Tg mice, we determined the percentage of cystic area in both kidneys through histomorphological analysis." (PMID 30585217, 2018).